CDK4 (cyclin dependent kinase 4)
Diseases named in the same sentence as CDK4 in open-access papers (continued):
Sharing a sentence is not in itself a finding about the gene and the disease.
chondrosarcoma (continued). "The enhanced levels of CDK4 were interlinked with malignant metastasis and undesirable prognosis of chondrosarcoma patients." (PMID 30808351, 2019). "By specifically knocking down CDK4 expression using siRNA, chondrosarcoma cell growth and phosphorylation of Rb were both suppressed." (PMID 30808351, 2019). "Due to the close relationship between CDK4 expression and the prognosis of patients with chondrosarcoma, we then explored its expression in human chondrosarcoma cell lines and the potential roles of CDK4 in human chondrosarcoma cell growth." (PMID 30808351, 2019). "Intriguingly, amplification of 12q13 is a common and consistent genetic aberration in advanced chondrosarcomas and the gene for CDK4 is localized at 12q13." (PMID 30808351, 2019). "Upon the validation of clinical significance of CDK4 in both chondrosarcoma samples and cell lines, we further assessed CDK4 selective inhibitor, palbociclib, in the treatment of chondrosarcoma." (PMID 30808351, 2019). "Our results indicate the significant role of CDK4 as potential therapeutic target during chondrosarcoma treatment." (PMID 30808351, 2019). "In chondrosarcoma, previous study showed the shRNA-mediated down-regulation of CDK4 expressions led to a dramatic attenuation in terms of cell viability and growth among OUMS27, SW1353 and CH2879 cell lines." (PMID 30808351, 2019). "The inhibitory expression of CDK4 by siRNA or palbociclib on cell proliferation, invasion, migration, apoptosis and cycle arrest of chondrosarcoma were determined by MTT, wound healing, transwell and flow cytometry." (PMID 30808351, 2019). "In summary, these data highlight CDK4 inhibitors, such as palbociclib, as potential promising therapeutics in the treatment of human chondrosarcoma." (PMID 30808351, 2019). "CDK4 was also highly expressed in human chondrosarcoma cell lines and its inhibition by specific siRNA and palbociclib lead to a decrease in cell proliferation, accompanied by the phosphorylation of Rb." (PMID 30808351, 2019). "In this study, the proliferation of chondrosarcoma cells was decreased by inhibiting CDK4 by siRNA." (PMID 35163019, 2022). "CDK4 was found to express significantly in human chondrosarcoma samples." (PMID 30808351, 2019). "Furthermore, for confirmation of the production of CDK4 as well as investigate its position in chondrosarcoma cells subcellularly, we employed immunofluorescence analysis in CS-1 and SW1353 cells." (PMID 30808351, 2019). "Therefore, we determined the expressions of human CDK4 in chondrosarcoma samples and evaluated the treatment effects of palbociclib in a chondrosarcoma xenograft mouse model." (PMID 30808351, 2019). "Therefore, it is manifested that CDK4 inhibition by palbociclib treatment alleviates the survival and proliferation of chondrosarcoma cells via the enhanced promotion of cell apoptosis by G1 cell cycle arrest." (PMID 30808351, 2019). "Also, the enhanced expression of CDK4 is intimately correlated with malignant metastasis and unpleasant prognosis of chondrosarcoma patients." (PMID 30808351, 2019). "Collectively, we show the significant positive-expression of CDK4 in chondrosarcoma." (PMID 30808351, 2019). "Thus, we aim to investigate the level of CDK4 and accompanying therapeutic effects of palbociclib in chondrosarcoma." (PMID 30808351, 2019). "Collectively, we illustrated that attenuation of CDK4 expression could suppress chondrosarcoma cell proliferation in a CDK4/Rb dependent manner." (PMID 30808351, 2019). "However, the level of CDK4 and the treatment possibility in chondrosarcoma require further exploration." (PMID 30808351, 2019). "Thus, we examined cell cycle and apoptosis to explore the possible regulative mechanism of chondrosarcoma cell proliferation arrest after CDK4 abrogation." (PMID 30808351, 2019). "Only the CDK4/Rb upregulation is present in nearly all high-grade central chondrosarcomas and might have the greatest potential for targeted treatment." (PMID 30808351, 2019).
chondrosarcoma (continued). "Since the results from TMA assay indicated that the level of CDK4 was dramatically correlated with the metastasis stage of patients suffered with chondrosarcoma, we therefore investigated the vital significance of CDK4 in the migration and invasion of chondrosarcoma cells in vitro." (PMID 30808351, 2019). "In light of our findings on the clinical chondrosarcoma samples and the pre-clinical inhibitory effects of CDK4 inhibition by palbociclib against tumor proliferation, migration and invasion, we hypothesized that palbociclib might suppress tumor development in vivo." (PMID 30808351, 2019). "The positivity of IMP3, CDK4, MDM2 and β-catenin antibodies was directly proportional to the increase of histological grade in Chondrosarcoma." (PMID 39368400, 2024). "The significant immunoexpression of IMP3, CDK4 and MDM2 in metastatic Chondrosarcoma and the lower survival in those with positivity for MDM2 suggest a possible association of these proteins with tumor aggressiveness." (PMID 39368400, 2024). "Thus, CDK4 might be an attractive target for alternative anticancer therapy in chondrosarcoma." (PMID 30808351, 2019). "However, the potential role of CDK4 in chondrosarcoma is still not clear and there is no data evaluating palbociclib in chondrosarcoma treatment." (PMID 30808351, 2019).
head and neck cancer (12 papers, 2012 to 2025). A primary or metastatic malignant neoplasm affecting the head and neck. "This suggests that CDK4 novel germline mutations observed in study may play a different and important role in squamous cell carcinoma of head and neck cancer in Pakistani population." (PMID 22932448, 2012). "Our previous studies in head and neck cancer identified copy number alterations in CDKN2A and/or CDK4 as predictive biomarkers and molecular correlates of response to abemaciclib." (PMID 40753072, 2025). "Past studies have shown that cyclin-dependent kinase 4 and 6 (CDK4 and CDK6) are generally overexpressed in various tumor cells and related to the increase of cyclin A in head and neck carcinomas." (PMID 33921647, 2021). "The patient with the FANCL (head and neck cancer) received olaparib and experienced a TTF for 12 months until progress, whereas the FA patient with CDK4/CCND1 amplification deceased after 13 months, with the first treatment being olaparib (6 months) and then palbociclib (7 months)." (PMID 38136436, 2023). "In contrast, CDK4 amplification in head and neck cancers is not prominent with 2.1% of 900 cases showing amplification and 2.4% showing mutation of the gene." (PMID 29464035, 2018). "Therefore, it was not surprising that HPV+ head and neck cancer cells were completely resistant to chemical CDK4/6 inhibitor." (PMID 27233076, 2016). "To begin determining whether HPV+ head and neck cancer cells are sensitive to roscovitine due to specific CDK inhibition, we assessed the response of HPV-positive and HPV-negative cells to another broad CDK inhibitor, flavopiridol, as well as to specific CDK1/2 and CDK4/6 inhibitors." (PMID 27233076, 2016).
adenoma (11 papers, 2011 to 2025). A neoplasm arising from the epithelium. "For example, in a mouse model of adenoma formation, Apc dysfunction causes an increase in Cyclin D2 and CDK4 expression and a corresponding increase in hyperphosphorylated Rb35." (PMID 30655555, 2019). "Recent work in our laboratory has shown that the cyclin D2-cyclin-dependent kinase 4/6 (CDK4/6) complex promotes hyperproliferation in Apc deficient intestinal tissue and ApcMin/+ adenomas." (PMID 21288356, 2011). "In these experiments, we compared the effects of Cdk4 pathway blockade on the number and size of adenomas in the Apc−/+Cdk+/+ with Apc−/+Cdk4−/− mice to characterize the role of the Cdk4 pathway in tumor development in vivo." (PMID 23530816, 2013). "In the present study, silibinin has inhibitory effects on the Cdk4 pathway and appears to mediate at least some of its effects through the cell cycle, proliferation of adenomas, and apoptosis." (PMID 23530816, 2013). "Dietary supplementation with silibinin (0.2%) resulted in a decrease in activity of the Cdk4 pathway and markedly reduced adenoma formation in Apc−/+ mice." (PMID 23530816, 2013). "This demonstrates that the Cdk4 pathway is important in the development or maintenance of adenomas in Apc−/+ mice." (PMID 23530816, 2013). "We conclude that indeed there is prominent expression of Cdk4 pathway components throughout adenoma epithelium." (PMID 23530816, 2013). "Double mutant mice exhibited significantly reduced adenomas, compared with Apc−/+Cdk4+/+ mice along their entire small and large intestine at 120 days of age." (PMID 23530816, 2013). "We have shown that cyclin D1, and Cdk4 expression is markedly reduced in mature epithelium at the luminal surface but clearly present within adenomas." (PMID 23530816, 2013). "Moreover, in mice treated with AOM, there was a marked increase in the number of cells showing immunoreactivity for cyclin D1 and cyclin‐dependent kinase 4 (Cdk4) in early lesions and adenomas." (PMID 40548181, 2025). "In addition, looking at available transcriptome data sets, a significantly higher CDK4 expression can be likewise observed in ACC vs. both adenomas and NAG." (PMID 32373071, 2020). "Unbiased analysis of the MYC targets V2 gene set revealed clusters correlated with the tumor histopathology, and adenocarcinoma-derived PDOs exhibited the high expression of distinct genes from adenoma-derived PDOs related to cellular proliferation, including CDK4, PLK1 and 4, MCM4, and MYC." (PMID 33060766, 2020). "CDK4 overexpression has been detected in intestinal adenomas and is associated with increased cell proliferative activity in premalignant neoplastic cells, which indicates that CDK4 may contribute to the malignant progression of adenomas." (PMID 31736743, 2019). "Furthermore, we found silibinin effectively opposes Cdk4 pathway activation at several points and administration as a chemopreventive agent resulted in reduced cell proliferation, increased apoptosis, and reduced adenoma development in Apc−/+ mice." (PMID 23530816, 2013). "Immunohistochemical findings showed nuclear positivity for a murine double minute 2 (MDM2) and cyclin-dependent kinase 4 (CDK4) and negativity for pleomorphic adenoma gene 1 (PLAG1)." (PMID 39109289, 2024). "CDK9 and CDK18 were upregulated in NR5A1-adenomas, whereas CDK4 and CDK7 were upregulated in POUF1-adenomas." (PMID 35260162, 2022). "For example, it is know that CDK4 activation in CDK4R24C/R24CApc+/min mice leads to significant increased in tumor vascularity in comparison to CDK4+/+Apc+/min mice or APC+/min mice, while knocking out CDK4 in APC+/min mice reduces adenoma development." (PMID 35002699, 2021). "The pattern of Cdk4 and cyclin D1 staining was strongest in the crypts and adenomas and almost absent from the villi." (PMID 23530816, 2013).
cholangiocarcinoma (11 papers, 2013 to 2025). A carcinoma that arises from the intrahepatic biliary tree (intrahepatic cholangiocarcinoma) or from the junction, or adjacent to the junction, of the right and left hepatic ducts (hilar cholangiocarcinoma). "A patient with a mixed hepatocellular- cholangiocarcinoma and amplification of CDK4 was treated with palbociclib and obtained a long-lasting partial response for 16 months." (PMID 40699853, 2025). "The effects of CDK4/6 inhibitors on cholangiocarcinoma (CCA) cell lines have indeed been explored in a limited number of studies, and the results have been somewhat conflicting or inconclusive." (PMID 38730642, 2024). "Induction of G0/G1 cell cycle arrest in cholangiocarcinoma cells by vitamin D analogues is mediated by upregulation of p27 and downregulation of CDK4, CDK6, and cyclin D3." (PMID 37561808, 2023). "Cyclin D, CDK4 and CDK6 mRNA expressions were up-regulated in cholangiocarcinoma tissues compared with adjacent normal epithelium." (PMID 40699853, 2025). "In cholangiocarcinoma cells, PTK7 depletion affected the level of cell-cycle related proteins, increasing Cdk2, Cdk4, Cdk6, and cyclin D1 and decreasing p16, p21, and p27, whereas it increased mitochondrial-dependent apoptosis." (PMID 25962058, 2015).
pneumonitis (11 papers, 2021 to 2026). An inflammatory process affecting the lung parenchyma. "Despite early detection and intervention, in our study, one patient died (0.22% of all 464 patients receiving CDK4/6 inhibitors) due to ILD-related complications, emphasizing the potentially life-threatening nature of CDK4/6 inhibitor-associated pneumonitis." (PMID 40142360, 2025). "published a systematic review and meta-analysis evaluating the overall incidence and risk of ILD/pneumonitis related to CDK4/6 inhibitors in RCTs." (PMID 37954071, 2023). "Radiological findings and ILD subtypes in CDK4/6i-associated pneumonitis." (PMID 40142360, 2025). "This case emphasizes the importance of early recognition of pneumonitis in patients on CDK4/6 inhibitors." (PMID 42137675, 2026). "Here, we report a case of an Asian female who developed pneumonitis after receiving adjuvant chest RT and CDK4/6i in a curative setting." (PMID 40430137, 2025). "Small case series have reported severe pneumonitis in patients receiving combination of CDK4/6i and chest RT, primarily in the context of metastatic breast cancer treated with low-dose palliative RT." (PMID 40430137, 2025). "The image of the lung window revealed subsegmental atelectasis, consolidation, and fibrotic changes in the left upper lung and lower lung, with suspected radiation- and CDK4/6i-induced pneumonitis." (PMID 40430137, 2025). "The occurrence of pneumonitis was first described in clinical trials and case reports, which included also fatal cases of pneumonia in patients treated with CDK4/6 inhibitors." (PMID 37954071, 2023). "Although data on pulmonary toxicity with CDK4/6 inhibitors are scant, recent case reports have described the potential occurrence of pneumonitis, including fatal cases." (PMID 33150548, 2021). "In the event of severe ILD/pneumonitis, discontinue the CDK4/6i." (PMID 37366894, 2023). "While lung toxicity is relatively rare when CDK4/6i is used alone, ILD or pneumonitis is an uncommon but potentially severe adverse effect." (PMID 40430137, 2025). "When looking at the pneumotox.com (last accessed April 2, 2024), a standard reference for ILD, the statement “pneumonitis/ILD” is reported for Palbociclib and Abemaciclib, whereas a general reference to the FDA warning on CDK4/6 inhibitors as a class is mentioned for Ribociclib." (PMID 41458615, 2025). "Recently, on September 13th, 2019, the FDA issued a warning about rare but severe lung inflammation with CDK4/6 inhibitors, based on cases of ILD and pneumonitis identified in the manufacturers’ completed and ongoing clinical trials and the post-marketing safety databases." (PMID 33150548, 2021). "A recent review by the FDA suggests that the occurrence of ILD/pneumonitis may also be a class effect; rates of ILD/pneumonitis reported in MONARCH 2 and 3 are similar to those observed in studies of other CDK4 and 6 inhibitors." (PMID 33392835, 2021).
skin cancer (11 papers, 2014 to 2023). "Using this pan-cancer study, our group has provided a comprehensive preliminary demonstration of the oncogenic effects of the CDK4 gene on different human skin tumors." (PMID 34422248, 2021). "Through literature search, we have not found any research from the perspective of basic analysis of all tumors, especially from the perspective of human skin tumors, to retrieve the literature on CDK4 pan-cancer analysis." (PMID 34422248, 2021). "Therefore, in the next step, we can study the specific mechanism or pathway of CDK4 in the occurrence and development of related skin tumors to see if there is a new breakthrough or discovery." (PMID 34422248, 2021). "Although the evidence based on current human, animal, or molecular biology can explain some of the relationships between CDK4 and cancer, there is no pan-cancer analysis of the gene CDK4 in human skin tumors." (PMID 34422248, 2021). "Interestingly, it was reported that in A431 skin cancer cells, EGCG did not alter the levels of p27, CDK2, and Cyclin D1 but did show inhibition of cell growth in vitro by increasing p21 and a decrease in CDK4." (PMID 37960113, 2023).
squamous cell carcinoma (11 papers, 2012 to 2022). A carcinoma arising from squamous epithelial cells. "Cdk4 is part of the cyclin-dependent kinase family, and overexpression of Cdk4 in mouse skin results in increased susceptibility to squamous cell carcinoma development in a chemically induced carcinogenesis model." (PMID 25961580, 2015). "To verify whether the Arg24Cys mutation in the CDK4 was present in squamous cell carcinoma, we analyzed a portion of exon 2 of the CDK4, where this mutation mapped by PCR-SSCP and subsequent sequence analysis." (PMID 22932448, 2012). "Furthermore, to determine association of novel mutations in CDK4 and risk of squamous cell carcinoma of head and neck, we performed polymerase chain reaction, single strand conformation polymorphism (PCR-SSCP) and sequence analysis." (PMID 22932448, 2012). "In conclusion, two novel mutations were found in N terminal domain which indicates that CDK4 mutation may play a major role in the development and progression of squamous cell carcinoma of head and neck." (PMID 22932448, 2012). "Urothelial carcinoma showed significantly higher percent and score of CDK4 expression compared to both cases of cystitis and squamous cell carcinoma (p<0.05)." (PMID 32102537, 2020). "Squamous cell carcinoma showed higher score of CDK4 expression compared to both chronic cystitis and urothelial carcinoma, with statistically significant difference (p<0.001 by ANOVA test)." (PMID 32102537, 2020). "Aim of study was to investigate a possible disruption of Rb suppression pathway by germline mutational analysis in the p16-binding and cyclin D1 binding domain of CDK4 in squamous cell carcinoma of head and neck in Pakistani population." (PMID 22932448, 2012). "To investigate whether alterations of the CDK4 were present in the squamous cell carcinoma of head and neck, we screened the coding regions (exons 1–8) as well as intron/exon boundaries of CDK4 using PCR-SSCP." (PMID 22932448, 2012). "In this study, we determined the effect of the CDK4/6 inhibitor, ribociclib (or LEE011), on P-glycoprotein (P-gp)-mediated MDR in the human epidermoid carcinoma MDR cell line, KB-C2, which is widely used for studying P-gp-mediated MDR in cancers." (PMID 35450042, 2022). "Interestingly, JNK function is required for Cdk4 upregulation in cellular systems with NF-κB downregulation, a component of squamous cell carcinomas, suggesting that JNK, Cdk4, and PKC may comprise a regulatory loop crucial in promoting neurogenesis and pro-survival signaling." (PMID 25659151, 2015).